HOXA10 (homeobox A10)
Diseases named in the same sentence as HOXA10 in open-access papers (continued):
Sharing a sentence is not in itself a finding about the gene and the disease.
endometriosis (continued). "In patients affected by endometriosis, the expression of HOXA10 is decreased during the secretory phase, and, as the result, uterine receptivity is decreased and endometriosis-related infertility occurs." (PMID 36901685, 2023). "Hypoacetylation of H3/H4 within promotor regions of target genes known to be downregulated in endometriosis, such as HOXA10." (PMID 37108664, 2023). "High HOXA10 DNA methylation level was observed in the endometrium tissue of women with endometriosis in all the included studies." (PMID 36979165, 2023). "The literature search was done using PubMed, Scopus, EBSCOhost, and Science Direct applying (HOXA10 OR “homeobox A10” OR “HOXA-10” OR HOX1) AND (“DNA methylation” OR methylation) AND (endometriosis OR endometrioma) as keywords." (PMID 36979165, 2023). "The identification of HOXA10 DNA methylation level has provided new insight into more potential treatments for endometriosis patients." (PMID 36979165, 2023). "In all case-control studies included in this systematic review, the methylation level of HOXA10 in eutopic endometrium collected during the secretory phase is significantly higher in endometriosis patients compared to normal individuals." (PMID 36979165, 2023). "The first discovered evidence showed that the promoter of the HOXA10 gene is hypermethylated in women with endometriosis compared to healthy individuals." (PMID 37108664, 2023). "The protein and mRNA expression of the vascular endothelial growth factor (VEGF), matrix metalloproteinase-9 (MMP-9), the endometrial receptivity markers, LIF and HOXA10, were measured in the endometrium of rats with endometriosis." (PMID 35273494, 2022). "Hypermethylation of the HOXA10 promoter region is also observed in the mouse uterus with induced endometriosis." (PMID 35203298, 2022). "Molecular mechanisms underlying the impaired uterine receptivity in endometriosis are mainly increased inflammatory cytokine and abnormal implantation markers, with LIF and HOXA10 playing important roles in embryo implantation and development." (PMID 35273494, 2022). "Metformin also significantly upregulated LIF and HOXA10 expression in endometrium from rats with endometriosis." (PMID 35273494, 2022). "In patients with endometriosis, HOXA10 gene hypermethylation was confirmed in three regions, rich in CpG islands in eutopic endometrium." (PMID 35409163, 2022). "A well-known PGR target, HOXA10, reduces its expression in the eutopic endometrium with endometriosis." (PMID 35203298, 2022). "In the endometrium of submucosal UFs, and intramural UFs, there were hypermethylated sites within the HOXA10 gene compared to controls, whereas in women with endometriosis HOXA10 gene was hypomethylated." (PMID 35269864, 2022). "With the diminished expression of HOXA10 in endometriosis, the increased level of endometrial EMX2 directly affects endometrial cell proliferation and function during the peri-implantation period, resulting in aberrant implantation." (PMID 36387918, 2022). "In the promoter region of the HOXA10 gene, specific epigenetic modifications in the secretory phase in patients with endometriosis have been identified." (PMID 35409163, 2022). "Numerous evidence show that endometriosis is an epigenetic disease, the first of which shows that the promoter of the HOXA10 gene is hypermethylated in the endometrium of women with endometriosis when compared to healthy women without the disease." (PMID 35807280, 2022). "In humans, hypermethylation of HOXA10 was also identified in the endometrium of women with endometriosis." (PMID 36387918, 2022). "Both murine and baboon endometriosis models showed hypermethylation of the promoter region of HOXA10 and decreased expression of HOXA10 genes in the eutopic endometrium." (PMID 36387918, 2022). "The expression of HOXA-10, an endometrial morphogenesis gene, is significantly decreased in women with endometriosis compared to controls." (PMID 36232341, 2022).
endometriosis (continued). "Our research partly illustrated the role of HOXA10 in cholesterol synthesis in endometriosis, which provides new insights for the development and treatment for OEMs." (PMID 35546998, 2022). "Decreased expression of HOXA10 in the endometrium during the window of implantation has been found in women with endometriosis." (PMID 35273494, 2022). "In the study by Rekker and coworkers, the overexpression of miR-139-5p induced a down-regulation of HOXA10, which is suppressed in the endometriosis eutopic endometrium, specifically within the stromal cells." (PMID 35406659, 2022). "A study revealed decreased HOXA10 expressions in endometrial samples of patients with uterine fibroids, unexplained infertility, and endometriosis in all patient groups." (PMID 36246072, 2022). "Studies on Hoxa10/11 genes reported a role not only during Müllerian duct differentiation but also blastocyst implantation and development, the hormone cycle, endometriosis and hydrosalpinx." (PMID 33763415, 2021). "HOXA10, estrogen receptor α, and progesterone receptor are highly expressed in rectosigmoid endometriosis lesions, which are characteristic lesions of DIE." (PMID 34367069, 2021). "HOXA10 was abnormally expressed in ectopic endometrial tissues and had different expression patterns in different phenotypes of endometriosis." (PMID 34367069, 2021). "Emx2 expression persists into mouse and human adulthood, is regulated by HoxA10 and is involved in the reproductive hormone cycle, blastocyst implantation and endometriosis." (PMID 33763415, 2021). "For example, alternation of HOXA10 and HOXA11 expression has been identified as a mechanism of infertility associated with endometriosis." (PMID 33667269, 2021). "The third gene is HOXA10 (homeobox A10), whose expression is downregulated in endometriosis but in late gestation is required for proper placental differentiation and function." (PMID 33842847, 2021). "Alteration in HOXA10 expression has been identified in several gynaecological disorders such as endometriosis, polycystic ovary syndrome, and other conditions related to abnormal implantation." (PMID 32685419, 2020). "Homeobox A10 (HOXA10) is a transcription factor critical in processes such as endometriosis, embryogenesis, and cell differentiation." (PMID 32019103, 2020). "HOXA10, a P4 target decreased in the endometrium of women with endometriosis and required for fertility in mice, was also identified as a direct regulator of αv/β3 integrin expression." (PMID 31387263, 2019). "Previous studies have proven that the expression of HOXA10 gene in the eutopic endometrium is altered in women with endometriosis." (PMID 30288484, 2018). "Patients with endometriosis exhibit a failure to increase expression of HOXA10 in the mid luteal phase, at the peak of the implantation window." (PMID 30555421, 2018). "The aim of this study was to evaluate the expression of miR-135a and its relationship with the level of HOXA10 gene expression in both endometrial ectopic and eutopic tissues in patients with endometriosis compared to the control samples." (PMID 30288484, 2018). "It has been evidenced that the HOXA10 gene is targeted by miR-135a that was increased significantly in endometriosis." (PMID 30288484, 2018). "Szczepańska showed the levels of HOXA10 gene expression in the eutopic tissue of infertile women with endometriosis have significantly decreased compared with control subjects in line with ours." (PMID 30288484, 2018). "HOXA10 expression is lower in the mid-secretory endometrium during the implantation window in endometriosis patients, but the levels are restored after surgical resection of endometriotic tissue." (PMID 30487429, 2018). "Hypermethylation of the HOXA10 gene promoter is, indeed, one of the potential molecular mechanisms silencing HOXA10 expression in the endometrium of patients with endometriosis." (PMID 30309386, 2018).
endometriosis (continued). "Among the genes that become the target of the miR-135a and are subjected to changes in the endometrium of patients with endometriosis is HOXA10 gene which is expressed in the endometrium in response to steroid hormones." (PMID 30288484, 2018). "Leaving from this background, in this work, we have analyzed the methylation status of HOXA10 gene regulation regions in a cohort of endometriosis patients respect to a control group of healthy women." (PMID 30309386, 2018). "The aim of this study was to evaluate the expression profile of miR-135a and its relationship with the level of HOXA10 gene expression in both endometrial ectopic and eutopic tissues in patients with endometriosis compared to controls." (PMID 30288484, 2018). "Endometrial receptivity is related to integrin expression of the endometrium; however, women with endometriosis have reduced expression of αvβ3, possibly due to decreased HOXA10." (PMID 30104541, 2018). "In this study, we have evaluated the methylation status of HOXA10 gene regulation regions in a cohort of 22 endometriosis patients respect to a control group of 6 healthy women." (PMID 30309386, 2018). "An IPA network of differentiating EBs confirmed that genes related to endometrial and endometriosis development, including Hoxa10, are expressed in EBs." (PMID 28716123, 2017). "In women with endometriosis, HOXA10 expression is significantly decreased in the eutopic endometrium during the secretory phase, indicating functional defects in uterine receptivity." (PMID 24927773, 2014). "These miRNAs were predicted and validated to target HOXA10, a key mediator of endometrial receptivity, the expression of which was simultaneously repressed in the endometrium of women with endometriosis." (PMID 24927773, 2014). "The deficient expression of HOXA10 and HOXA11 in infertile women with endometriosis and in animal models has been demonstrated." (PMID 22233680, 2012). "The hypermethylation of HOXA10 DNA regulatory sequences have been well documented to date in humans, and in murine and baboon endometriosis." (PMID 22233680, 2012). "Previously, we reaffirmed that DNA hypermethylation can be one of the mechanisms silencing HOXA10 expression in the mid-secretory endometrium in infertile women with endometriosis." (PMID 22233680, 2012). "We have examined the expression of HOXA10 in eutopic endometrium of baboons with experimental endometriosis." (PMID 17118171, 2006). "Distinct endometriosis subtypes exhibit different levels of HOXA10 expression." (PMID 40305321, 2025). "Whilst we have not identified any investigations exploring the global DNA methylation patterns in women with RIF, altered DNA methylation of ER-related genes, such as the Homeobox A10 (HOXA10) gene, have been reported in the eutopic endometrium of women with endometriosis." (PMID 39858500, 2025). "Reduced endometrial epithelial and stromal HOXA10 expression during the luteal phase have also been reported in a number of other conditions associated with infertility, such as RIF, recurrent miscarriage, and endometriosis." (PMID 39858500, 2025). "Similarly, partial methylation of 10.7% in the promoter region of Hoxa10 has been reported in the eutopic endometrium of a mouse endometriosis model." (PMID 39858500, 2025). "Hypermethylation Hoxa10/HOXA10 have also been observed in animal models of endometriosis." (PMID 39858500, 2025). "A mid-secretory-phase reduction in TET1 mRNA expression in the eutopic endometrium of infertile women with endometriosis may be a potential mechanism for the hypermethylation of HOXA10." (PMID 39858500, 2025). "In addition, aberrant DNA methylation in endometriosis induces the expression of many genes, including homeobox A10 (HOXA10), an estrogen beta receptor gene, a progesterone receptor, aromatase, HOXC6, and ALDH1A2." (PMID 40003570, 2025).
endometriosis (continued). "Moreover, molecular alterations in the eutopic endometrium of women with endometriosis, such as downregulation of HOXA10/A11, further compromise implantation by disrupting decidualization, immune cell function, and cytokine signaling." (PMID 40305321, 2025). "Furthermore, impaired expression levels of HOXA10 and prokineticins have been associated with various infertility-related conditions, including unexplained infertility, PCOS, endometriosis, and recurrent pregnancy loss." (PMID 39915377, 2025). "Indeed, in their research, differential methylation profiles in endometrial tissue of women with endometriosis were identified, involving genes like HOXA10, PR, and ESR1, which are crucial for normal reproductive function." (PMID 39311136, 2024). "HOXA-10, aromatase, progesterone receptors, matrix metalloproteinases (MMPs), and alphaV beta 3-integrin are some of the genes with altered expression in eutopic endometrium in women with endometriosis and fertility disorders." (PMID 38813329, 2024). "However, more effects from the methylation of HOXA10 should be further studied to understand the pathogenesis of endometriosis robustly." (PMID 36979165, 2023). "Aberrant DNA methylation has been reported in endometriotic tissue in genes implicated in the hormonal and inflammatory factors of endometriosis pathogenesis (estrogen and progesterone receptors ERα, Erβ, and Prβ, the aromatase CYP19, the homebox protein HOXA-10, and the cyclooxygenase COX-2)." (PMID 37895084, 2023). "Thus, a comprehensive literature search was conducted to identify the DNA methylation level of HOXA10 among endometriosis patients across populations." (PMID 36979165, 2023). "However, there is still a need to report the variation in the HOXA10 DNA methylation level among endometriosis patients across populations." (PMID 36979165, 2023). "However, additional studies are required to reveal the HOXA10 mechanism in the pathogenesis of endometriosis and to confirm its suitability as a biomarker for the diagnosis and prognosis of endometriosis." (PMID 36979165, 2023). "However, as reported by all the included studies, the HOXA10 DNA methylation level in endometriosis women increases during the secretory phase." (PMID 36979165, 2023). "Thus, it is estimated that the HOXA10 expression level was downregulated in the eutopic endometrium but was upregulated in the ectopic endometrium of endometriosis patients." (PMID 36979165, 2023). "Similarly, miR-135a and miR-135b were shown to regulate the expression of homeobox A10 (HOXA10) in women with endometriosis." (PMID 37834449, 2023). "Hence, a comprehensive literature search to identify the DNA methylation level of HOXA10 among endometriosis patients across populations was performed." (PMID 36979165, 2023). "Thus, further functional studies on the pathways related to the effect of HOXA10 in endometriosis are warranted." (PMID 36979165, 2023). "Aberrant hypermethylation of HOXA10 has been reported to play a role in endometriosis." (PMID 36979165, 2023). "However, more studies are needed to expose the HOXA10 mechanism in the pathogenesis of endometriosis." (PMID 36979165, 2023). "However, promoter hypermethylation of HOXA10 in the endometrium turns out to occur not only in patients with endometriosis but also those with Asherman’s syndrome, intramural and submucosal uterine myoma, as well as endometrial polyps." (PMID 36830705, 2023). "Interestingly, low methylation level was reported in women with endometriosis, and various treatments used in endometriosis alter HOXA10 regulation." (PMID 36979165, 2023). "Another knowledge gap is also seen in the regulation of HOXA10 expression studies in endometriosis." (PMID 36979165, 2023). "As one of the epigenetic modification, DNA methylation modification is the early event of diseases, indicating that HOXA10 methylation may be the early indicator of endometriosis." (PMID 35546998, 2022).
endometriosis (continued). "In addition, the leukemia inhibitor factor (LIF) and HOXA10 genes are also distinguishing markers of endometriosis (decrease) and endometrial receptivity (increase)." (PMID 35273494, 2022). "In connection with diminished expression of HOXA10 in the endometriosis, the increased level of endometrial mRNA EMX2 is found during the peri-implantation period, which may result in the aberrant course of the embryo’s implantation process." (PMID 35409163, 2022). "Taken together, the expression of LIF and HOXA10 in the endometrium may affect receptivity of endometrium in women with endometriosis." (PMID 35273494, 2022). "The reduction of HOXA10 in women with endometriosis is related to defects in uterine receptivity, which could be an explanation for the low fertility rate of these women." (PMID 35807280, 2022). "Hsa-mir-135a and HOXA10 show an inverse correlation in their expression patterns in endometriosis, with HOXA10 being significantly decreased in the patient eutopic endometrium in the secretory phase, and significantly increased in the ectopic lesion in both the proliferative and secretory phases." (PMID 36009038, 2022). "This suggested that HOXA10 may be involved in the pathogenesis of endometriosis and PCOS induced by prenatal androgen levels, increasing the possibility that AGD can be used as a predictive and diagnostic indicator for both disorders." (PMID 34367069, 2021). "Abnormal expression of HOXA10 and its downstream target genes leading to decreased endometrial receptivity are closely related to female infertility in the patients with gynecological diseases, such as endometriosis, adenomyosis, and hydrosalpinx." (PMID 34906165, 2021). "The first piece of evidence suggesting the role of epigenetic in the etiopathogenesis of endometriosis comes from studies reporting the hypermethylation of the HOXA10 gene promoter in eutopic endometrium of women with endometriosis as compared with healthy controls." (PMID 31717614, 2019). "Further confirming the comprehensive disruption of P4 signaling in endometriosis, HOXA10, IGFBP1, PLZF, MIG-6, and CRISPLD2, all PGR targets implicated in endometrial function based on mouse studies, have been shown to be dysregulated in endometriosis patients." (PMID 31387263, 2019). "Supporting this hypothesis there are several studies showing HOXA10 promoter hypermethylation and reduced HOXA10 expression in experimental endometriosis in baboons and in mice." (PMID 30309386, 2018). "In contrast, in the ectopic endometrium of patients affected by endometriosis, few methylation rates of HOXA10 gene promoter was detected than their eutopic endometrium of those patients, stated of the ectopic tissues contribute to a better etiopathologic understanding of endometriosis." (PMID 30288484, 2018). "Interestingly, it has been shown that in endometriosis patients a decrease in the expression of HOXA10 has been detected in the endometrium during the secretory phase." (PMID 30309386, 2018). "In women with endometriosis, the expression of the HOXA10 gene decreases dramatically, indicating a defect in uterine acceptance that may be responsible for reduced fertility in women with endometriosis." (PMID 30288484, 2018). "Elevations in estradiol, prostaglandins, HOXA10 expression, and prolactin, as well as progesterone resistance may reduce endometrial receptivity in endometriosis patients, thereby impeding implantation and contributing to their infertility." (PMID 30555421, 2018). "Therefore, even though hypermethylation of the HOXA10 promoter has been frequently found in different studies on endometriosis, other epigenetically altered genes should be considered more related to the pathogenesis of this disease." (PMID 30309386, 2018).